MIR100HG (mir-100-let-7a-2-mir-125b-1 cluster host gene)
Synonyms: AGD1; lncRNA-N2; linc-NeD125
Gene: Long non-coding RNA gene on chromosome 11 (122,028,325 to 122,556,721, reverse strand). Ensembl gene ENSG00000255248.
Gene Ontology:
Biological process: miRNA-mediated post-transcriptional gene silencing
Cellular component: RISC complex
Diseases named in the same sentence as MIR100HG in open-access papers:
MIR100HG is named in the same sentence as 53 diseases in open-access papers, as found by Europe PMC text mining. Sharing a sentence is not in itself a finding about the gene and the disease. The quoted sentences say what the papers report.
colorectal cancer (15 papers, 2019 to 2025). A primary or metastatic malignant neoplasm that affects the colon or rectum. "This RNA-binding protein-mediated regulatory mechanism resembles the MIR100HG/hnRNPA2B1/TCF7L2 axis in colorectal cancer, highlighting evolutionarily conserved regulatory logic across diverse biological processes." (PMID 41244234, 2025). "Particularly, MIR100HG over‐expression has been more prominent in advanced colorectal cancer compared with in early stage samples." (PMID 37487022, 2023). "Recent studies have demonstrated that A2B1 interacting with lncRNA MIR100HG stabilizes TCF7L2 mRNA in a m6A-dependent manner to promote colorectal cancer progression." (PMID 38017546, 2023). "Constitutive up‐regulation of β‐catenin in colorectal cancer cells has been found to decrease levels of primary and mature MIR100HG transcripts, while obstruction of β‐catenin activity has led to enhancement of their expression." (PMID 37487022, 2023). "MIR100HG has also been shown to be a potent EMT inducer in colorectal cancer, possibly contributing to cetuximab resistance and metastasis by activating the MIR100HG/hnRNPA2B1/TCF7L2 feedback loop." (PMID 36226248, 2022). "On the contrary, high levels of MIR100HG expression were found in colorectal cancer, osteosarcoma, and acute megakaryoblastic leukemia." (PMID 30886062, 2019). "In addition, LncRNA MIR100HG has been identified as a positive regulator of EMT in colorectal cancer cells, in which hnRNPA2B1, a recognized m6A binding protein, was further identified as a binding partner of MIR100HG." (PMID 37365581, 2023). "MIR100HG is expressed at high levels in triple-negative breast cancer, laryngeal squamous cell carcinoma, gastric cancer and colorectal cancer." (PMID 35127818, 2021). "The lncRNA MIR100HG has been studied as an oncogene in acute megakaryoblastic leukemia, and laryngeal squamous cell carcinoma (Huang, Zhang & Zhou, 2019), as well as for its role in mediating cetuximab resistance via Wnt/ β-catenin signaling in colorectal cancer." (PMID 33614260, 2021). "Indeed, MIR100HG promotes colorectal cancer progression and predicts poor prognosis." (PMID 33941855, 2021). "Previous studies had demonstrated that lncRNA MIR100HG was identified as an oncogene in various cancers, including breast cancer, hepatocellular carcinoma (HCC), gastric cancer, and colorectal cancer." (PMID 36911392, 2023). "MIR100HG promotes EMT, tumor invasion and metastasis of colorectal cancer cells." (PMID 35938036, 2022).
gastric cancer (12 papers, 2018 to 2024). A primary or metastatic malignant neoplasm involving the stomach. "We observed high MIR100HG expression was positively associated with clinical stage, tumor invasion, lymph node metastasis, and distant metastasis in gastric cancer patients." (PMID 30886062, 2019). "We found that MIR100HG expression is negatively associated with disease free survival (P=0.019) and overall survival (P=0.033) in TCGA gastric cancer cohort." (PMID 30886062, 2019). "Moreover, high MIR100HG expression was positively associated with clinical stage, tumor invasion, lymph node metastasis, and distant metastasis in gastric cancer patients." (PMID 30886062, 2019). "MIR100HG expression has also been reported to be elevated in gastric cancer tissues compared with normal gastric mucosa tissues." (PMID 37487022, 2023). "It is found that MIR100HG was highly expressed in gastric cancer by bioinformatics methods, and its expression was significantly related to the TNM stage, but not with lymph node metastasis (LNM) or age." (PMID 36212400, 2022). "Down-regulation of MIR100HG expression in gastric cancer inhibits proliferation, migration, and invasion of gastric cancer cells." (PMID 35024796, 2022). "The expression of MIR100HG in gastric cancer was measured by RT‐qPCR, and the results showed that compared with normal tissues, the expression of MIR100HG was increased in gastric cancer tissues." (PMID 32715641, 2020). "Based on reported studies and bioinformatic analyses, we have been suggested the potential role of CXXC4/ELK1/MIR100HG in gastric cancer." (PMID 32715641, 2020). "In gastric cancer, high expression of MIR100HG is positively correlated with clinical stage, tumour invasion and distal metastasis, thus potentially serving a potential prognostic biomarker for gastric cancer." (PMID 32715641, 2020). "Inhibition of the CXXC4/ELK1/MIR100HG pathway suppressed the immune escape of gastric cancer cells, highlighting a possible therapeutic target for the treatment of gastric cancer." (PMID 32715641, 2020). "For exploring the prognostic value of MIR100HG in gastric cancer patients, Kaplan–Meier method and log-rank test were executed to assess the correlation between MIR100HG expression and clinical outcome of gastric cancer patients at TCGA database and our study." (PMID 30886062, 2019). "Down-regulation of MIR100HG expression inhibits cell proliferation, migration and invasion in gastric cancer." (PMID 30886062, 2019). "We preliminarily investigated the effect of MIR100HG on gastric cancer cell proliferation, migration and invasion, and found down-regulation of MIR100HG expression inhibits cell proliferation, migration and invasion in gastric cancer." (PMID 30886062, 2019). "We observed that MIR100HG expression levels were obviously elevated in human gastric cancer cell lines compared with human gastric epithelial cell line (P<0.001)." (PMID 30886062, 2019). "The results suggested that down-regulation of MIR100HG expression significantly reduced gastric cancer cell migration and invasion (P<0.001)." (PMID 30886062, 2019). "In conclusion, MIR100HG is overexpressed in gastric cancer tissues and cell lines, and correlated with clinical progression and poor clinical outcome." (PMID 30886062, 2019). "Meanwhile, high MIR100HG expression served as an independent poor prognostic factor for gastric cancer patient’s overall survival." (PMID 30886062, 2019). "Further analyses have suggested MIR100HG as a possible prognostic factor for gastric cancer." (PMID 37487022, 2023). "Besides, MIR100HG levels have been negatively correlated with clinical outcome in TCGA gastric cancer samples and another cohort of patients." (PMID 37487022, 2023). "In gastric cancer, downregulation of MIR100HG inhibits cell proliferation and migration." (PMID 34335744, 2021). "Next, we verified the role of the CXXC4/MIR100HG/CDK18‐ERK1/2 axis in gastric cancer." (PMID 32715641, 2020).
gastric cancer (continued). "MIR100HG might shed lights on new targets for individualized immunotherapy for bladder cancer patients, and MIR100HG participates in the suppression of the immune escape of gastric cancer cells." (PMID 38602284, 2024). "TCF7L2 can promote gastric cancer metastasis by regulating PLAUR and forming a MIR100HG/hnRNPA2B1/TCF7L2 axis to promote CRC metastasis." (PMID 38818308, 2024). "In the context of gastric cancer, CXXC finger protein 4 has been shown to inhibit the CDK18‐ERK1/2 axis to inhibit the immune escape through modulation of ELK1/MIR100HG pathway." (PMID 37487022, 2023). "We found that MIR100HG expression was relatively increased in SGC7901, BGC-823 cell lines amongst four gastric cancer cell lines." (PMID 30886062, 2019). "It has been reported that MIR100HG has been used as proto-oncogene and RBPMS2 is used as a target for gastric cancer markers and cancer targeted therapy." (PMID 29301256, 2018). "Furthermore, we detected the expression of MIR100HG in a human gastric epithelial cell line (GES-1) and four human gastric cancer cell lines (MGC-803, SGC7901, BGC-823, AGS) through qRT-PCR." (PMID 30886062, 2019). "We first found MIR100HG expression was negative correlated with clinical outcome in gastric cancer patients from TCGA database or our study." (PMID 30886062, 2019). "Survival analysis showed MIR100HG expression was negative correlated with clinical outcome in gastric cancer patients from The Cancer Genome Atlas (TCGA) database or our study, and high MIR100HG expression served as an independent poor prognostic factor for gastric cancer patient’s overall survival." (PMID 30886062, 2019). "However, there was no report about the role of MIR100HG in gastric cancer." (PMID 30886062, 2019). "Interestingly, the high relevance of MIR100HG with immunotherapy, which is quite ‘hot’ in the presented heat map, has been confirmed in multiple cancers including osteosarcoma, laryngeal squamous cell carcinoma, triple‐negative breast cancer and gastric cancer." (PMID 33797188, 2021).
osteosarcoma (9 papers, 2019 to 2022). A usually aggressive malignant bone-forming mesenchymal neoplasm, predominantly affecting adolescents and young adults. "MIR100HG overexpression was associated with cetuximab resistance and poor prognosis in colorectal and cervical cancer patients, and it was found to promote cell proliferation in laryngeal squamous cell carcinomas, hepatocellular carcinomas, osteosarcomas, and triple-negative breast cancer." (PMID 36458289, 2022). "A previous study demonstrated that ELK1-induced upregulation of MIR100HG promotes the progression of osteosarcoma." (PMID 35123530, 2022). "In osteosarcoma cells, MIR100HG expression peaked during early G1 cell cycle phase, and MIR100HG silencing caused cell cycle arrest." (PMID 33941855, 2021). "In osteosarcoma cells, MIR100HG promotes proliferation by interacting with the EZH2 protein of the polycomb repressor complex-2, causing repression of LATS1/2, mediators of Hippo signaling." (PMID 33941855, 2021). "The prognostic significance of MIR100HG expression has been investigated in breast cancer, bladder cancer, cervical cancer, osteosarcoma, and head and neck squamous cell carcinoma." (PMID 30886062, 2019). "MIR100HG has been revealed overexpressed in osteosarcoma cell lines and patient samples." (PMID 36212400, 2022). "In addition, elevated expression of MIR100HG is correlated with poor prognosis of osteosarcoma." (PMID 32591022, 2020). "While we found that MIR100HG was equally distributed in cytoplasm and nucleus in normal lung fibroblasts, MIR100HG is predominantly located in the nucleus of human megakaryotic leukemia cells (CMK) and osteosarcoma (U2OS) cells." (PMID 31925944, 2020).
acute megakaryoblastic leukemia (8 papers, 2014 to 2022). Acute megakaryoblastic leukemia (AMKL) is a form of acute myeloid leukemia (AML) that occurs predominantly in childhood and particularly in children with Down syndrome (DS-AMKL). "For instances, MIR100HG suppression impairs the cell viability, thus attenuating the tumorigenesis of acute megakaryoblastic leukemia." (PMID 34381502, 2021). "It has been reported that down-regulation of MIR100HG in acute megakaryocytic leukemia may lead to inhibition of M-07e cell proliferation and induction of apoptosis and necrosis through up-regulation of TGFb expression." (PMID 35024796, 2022). "In acute megakaryoblastic leukemia, silencing of MIR100HG impaired cell proliferation." (PMID 33941855, 2021). "MIR100HG has been considered as oncogene in acute megakaryoblastic leukemia." (PMID 27863388, 2016).
breast carcinoma (7 papers, 2014 to 2023). "MIR100HG is involved in tumor proliferation, migration, and invasion in breast cancer, liver cancer, and laryngeal squamous cell carcinoma." (PMID 35024796, 2022). "For example, MIR100HG plays an oncogenic role in breast cancer by directly interacting with the promoter of p27 to form RNA‒DNA triplex structures, which attenuate the transcription of p2726." (PMID 36424455, 2022). "In analyzing expression profiles of breast cancer subtypes based on The Cancer Genome Atlas (TCGA) database, MIR100HG showed significantly higher expression in TNBC than in other subtypes of breast cancer." (PMID 30042378, 2018). "MIR100HG in The Cancer Genome Atlas (TCGA) and breast cancer cell lines showed higher expression in TNBC than in other tumor types with poor prognosis." (PMID 30042378, 2018). "Here, however, we showed that MIR100HG was more highly expressed in poor prognosis TNBC compared with other breast cancer subtypes." (PMID 30042378, 2018). "We also detected MIR100HG in various breast cancer cell lines and found higher expression in TNBC cells lines than in other cell types." (PMID 30042378, 2018). "Moreover, Kaplan–Meier survival analysis from the KM plot data of TNBC patients, but not of other breast cancer subtypes, showed that higher expression of MIR100HG was associated with lower survival rates." (PMID 30042378, 2018).
laryngeal squamous cell carcinoma (6 papers, 2021 to 2022). A squamous cell carcinoma that arises from the larynx. "MIR100HG may promote the proliferation, migration, and invasion of laryngeal squamous cell carcinoma (LSCC) through down-regulation of mir-204-5p." (PMID 35937989, 2022).
leukemia (6 papers, 2017 to 2022). A malignant (clonal) hematologic disorder, involving hematopoietic stem cells and characterized by the presence of primitive or atypical myeloid or lymphoid cells in the bone marrow and the blood. "Furthermore, hsa-miR-100 belonging to the miR-125b-1 cluster (chr11, MIR100HG host gene) and hsa-miR-125a-3p belonging to miR-125a cluster (chr19) were among the top ranked differentially expressed miRNAs, highlighting the involvement of the miR-125 family in the ERG-related leukemia phenotype." (PMID 28415578, 2017).
triple-negative breast carcinoma (6 papers, 2019 to 2025). An invasive breast carcinoma which is negative for expression of estrogen receptor (ER), progesterone receptor (PR), and human epidermal growth factor receptor 2 (HER2). "MIR100HG promotes the proliferation of nasopharyngeal carcinoma cells via the miR-136-5p/IL-6 axis and enhances the growth of triple-negative breast cancer cells through the miR-5590-3p/OTX1 axis." (PMID 40969769, 2025). "MIR100HG promotes the development of triple-negative breast cancer (TNBC) by regulating the P27 gene and sponging mir-5590-3p." (PMID 35937989, 2022). "In triple-negative breast cancer, reduced expression of MIR100HG leads to a reduction in cell proliferation." (PMID 34335744, 2021).
bladder cancer (5 papers, 2019 to 2024). "In the meantime, MIR100HG expression has been revealed to be positively related the tumor and clinical grades of bladder cancer patients, and restoration of MIR100HG boosts the biological functions of bladder cancer cells." (PMID 38602284, 2024). "Mechanistically, miR‐142‐5p can inhibit expression of CALD1 in these cells via a direct interaction and reverses the effects of MIR100HG over‐expression in proliferation of bladder cancer cells." (PMID 37487022, 2023). "An experiment in bladder cancer cells has shown that up‐regulation of MIR100HG efficiently promotes proliferation, migration and invasion of the 5637 bladder carcinoma cells, inhibits expression of miR‐142‐5p and induces expression of CALD1." (PMID 37487022, 2023). "Based on these results, high MIR100HG expression promotes the progression of bladder cancer cells in vitro, consistent with the results from the correlation analysis of clinicopathological parameters." (PMID 35127818, 2021). "This study confirmed the direct interaction between MIR100HG and miR-142-5p through dual luciferase assays, and further confirmed that the expression of miR-146b-5p in bladder cancer cells increased after MIR100HG knockout." (PMID 35127818, 2021). "MIR100HG is an independent prognostic factor for bladder cancer, with potential as a biomarker for the diagnosis and treatment of bladder cancer." (PMID 35127818, 2021). "Apart from a single study in bladder cancer, which has reported down‐regulation of MIR100HG in cancerous cells compared with their normal counterparts, most in vitro studies have indicated an oncogenic role for MIR100HG." (PMID 37487022, 2023). "Notably, survival prognosis analyses, Cox analysis and additional in silico methods have shown the importance of MIR100HG/miR‐142‐5p/CALD1 axis in bladder cancer development." (PMID 37487022, 2023). "While MIR100HG is upregulated or downregulated in brain tumor and bladder cancer." (PMID 36212400, 2022). "Compared with patients with bladder cancer presenting low MIR100HG expression levels, patients with bladder cancer presenting high MIR100HG expression levels were more likely to have a more advanced tumor status, grade and stage, which leads to disease progression and poor prognosis." (PMID 35127818, 2021). "As shown in the present study, MIR100HG is an essential cancer-promoting factor in bladder cancer." (PMID 35127818, 2021). "In addition, miR-142-5p inhibited CALD1 expression in bladder cancer cells through a direct association, and reversed the proliferation and CALD1 expression in 5,637 cells overexpressing of MIR100HG." (PMID 35127818, 2021). "Overexpression of MIR100HG increased the proliferation, migration and invasion of bladder cancer." (PMID 35127818, 2021). "However, the role of MIR100HG in the development of bladder cancer is poorly understood." (PMID 35127818, 2021). "The trends in the expression of MIR100HG and CALD1 were consistent with the transcriptome sequencing results, and their levels were up-regulated in bladder cancer." (PMID 35127818, 2021). "In addition, we further found that MIR100HG regulated CALD1 expression by targeting miR-142-5p, and the miR-142-5p mimic reversed the regulatory effect of MIR100HG overexpression on the proliferation of bladder cancer cells." (PMID 35127818, 2021).
hepatocellular carcinoma (5 papers, 2022 to 2026). A malignant tumor that arises from hepatocytes. "Another paper has demonstrated that high MIR100HG expression has a positive correlation with the Edmondson‐Steiner grading and TNM stage in hepatocellular carcinoma (HCC) patients, and depletion of MIR100HG impedes the HCC cell viability, migration, as well as invasion." (PMID 38602284, 2024).